ENSG00000280800 (novel transcript, similar to YY1 associated myogenesis RNA 1 YAM1)
Gene: Long non-coding RNA gene on chromosome 21 (8,210,384 to 8,211,306, reverse strand). Ensembl gene ENSG00000280800.
Gene Ontology:
Molecular function: structural constituent of ribosome
Cellular component: ribosome